CTLA4 (cytotoxic T-lymphocyte associated protein 4)
Diseases named in the same sentence as CTLA4 in open-access papers (continued):
Sharing a sentence is not in itself a finding about the gene and the disease.
tuberculosis (18 papers, 2009 to 2026). A chronic, recurrent infection caused by the bacterium Mycobacterium tuberculosis. "Furthermore, we found that up-regulation of circRNA-0003528 promoted tuberculosis associated macrophage polarization by promoting expression CTLA4, which was mediated by the down-regulation of miR-224-5p, miR-324-5p and miR-488-5p." (PMID 33318319, 2020). "Circ0003528 through miR-324-5p/CTLA4 axis could cause tuberculosis related macrophage polarization." (PMID 36035118, 2022). "A study on patients with tuberculosis has shown that the frequency of CTLA-4-expressing Treg cells is increased in blood circulation, and CTLA-4 blockade reverses the suppressive effects of Tregs." (PMID 34592958, 2021). "We studied the CTLA4 +6230 polymorphism in pulmonary tuberculosis (TB) for two reasons." (PMID 19609446, 2009). "Similarly, elevated levels of CTLA4 expression were observed in lymphocytes from patients with tuberculosis, and the blockade of CTLA4 was found to enhance the immune response to Mycobacterium tuberculosis infection." (PMID 39456732, 2024). "Therefore, CTLA-4 is a promising new target for immunotherapy for active tuberculosis." (PMID 38807592, 2024). "An early study comparing CTLA-4 expression between HIV-negative TB patients and healthy controls previously exposed to M. tuberculosis found CTLA-4 expression to be significantly reduced in TB patients compared with controls." (PMID 35595321, 2022). "In another study, the expression of CTLA-4 in CD4+ CD25+ Foxp3+ Treg cells was elevated both in the blood of patients with pulmonary tuberculosis and in the pleural cavity of individuals with tuberculosis pleurisy." (PMID 38807592, 2024). "PD-1 and CTLA-4 belong to the CD28-B7 superfamily, and their expressions on T cells are reportedly upregulated in persistent infections such as tuberculosis and HIV." (PMID 26974441, 2016). "Little is known about the expression of inhibitory molecules cytotoxic T-lymphocyte antigen-4 (CTLA-4) and programmed-death-1 (PD-1) on Mycobacterium tuberculosis (Mtb)-specific CD4 T-cells and how their expression is impacted by TB treatment." (PMID 27367521, 2016). "In Ghana, West Africa, we compared the frequencies of CTLA4 +6230 A/G and 6 haplotype-tagging SNPs in 2010 smear-positive, HIV-negative patients with pulmonary tuberculosis (TB) and 2346 controls matched for age, gender and ethnicity." (PMID 19609446, 2009). "PD-1, CTLA-4, TIM-3, LAG-3 and, TIGIT on both CD4+ and CD8+ T-lymphocytes in the peripheral blood of treatment-naïve individuals from four cohorts, including active pulmonary tuberculosis (TB), HIV-1 infection only, HIV-TB co-infected, and healthy volunteers from North India." (PMID 40872312, 2025).
vasculitis (18 papers, 2014 to 2025). "These increased anti-CTLA-4 antibodies may suppress Th1 cell function and may cause a relative Th2 cell activation, leading to immune complex-mediated vasculitis in patients with BD." (PMID 24991555, 2014). "As effector T cells and Treg function have a pivotal role in the development of autoimmune vasculitis, currently available CTLA4-Ig has been tested to evaluate the efficacy of achieving glucocorticoid-free remission in patients with relapsing vasculitis." (PMID 33251233, 2020). "Rashes were found in 17% of the patients, with a main distribution in the patients with LCH (n = 6) and JDM (n = 7), and also in the patients with SLE, drug-induced hypersensitivity reaction, vasculitis, SAVI and CTLA4 deficiency." (PMID 31969166, 2020). "Humanized mouse models have shown that dual immunotherapy of PD‐1/CTLA‐4 inhibitors induces severe interstitial nephritis and vasculitis compared with monotherapy, with CD4+ T cell aggregation in the affected tissues, consistent with the renal pathological phenotype in patients." (PMID 40787068, 2025). "Native AAV has been linked to single nucleotide polymorphisms in the CTLA-4 gene, highlighting one possible mechanism through which CTLA-4 inhibition may also lead to vasculitis." (PMID 38213548, 2023). "For example, abatacept in CTLA4 haploinsufficiency, LRBA and DEF6 deficiencies; tocilizumab in STAT3 GOF; JAK inhibitors in STAT3 and STAT1 GOF patients; alemtuzumab for CD25 deficiency; PIK3δ inhibitors for APDS or anti-TNFα therapy for vasculitis in ADA2 deficiency." (PMID 34447369, 2021). "Vasculitis has not been documented as an irAE after anti-PD-1/L-1 and/or anti-CTLA4; it is seen in <1% of cases, with large-vessel involvement in most of them." (PMID 40416866, 2025).
colorectal tumors (17 papers, 2016 to 2025). "BALB/c mice bearing CT26 colorectal tumors were treated with combined ICI (anti-cytotoxic T-lymphocyte-associated protein 4 (CTLA-4) and anti-programmed death 1 (PD-1))." (PMID 38130991, 2023). "ZQFZ upregulated the levels of CD4 and CD8 in the spleen and colorectal tumors and decreased the expression levels of cytotoxic T-lymphocyte-associated protein 4 and programmed death-ligand 1 in colorectal tumors." (PMID 35680568, 2022). "We have recently reported using 225Actinium-labeled anti-CCR8 IgG for killing CCR8+ ti-Tregs in murine colorectal tumors which synergized with subsequent anti-CTLA4 ICI." (PMID 41302499, 2025). "Significantly, the co-administration of AE-MGNPs and anti-CTLA-4 antibody (α-CTLA-4) resulted in impressive tumor regression in CAFs-rich colorectal tumor models." (PMID 38581017, 2024). "A combination of AE-MGNPs and anti-CTLA-4 antibody greatly elicited a striking level of antitumor T-cell response to suppress tumor growth in CAFs-rich colorectal tumor models." (PMID 38581017, 2024). "For example, CD8+ Tregs isolated from prostate or colorectal tumours are commonly characterized by CTLA-4 expression and TGF-β production, suppressing CD4+ T cell proliferation, Th1 cell expansion and their IFN-γ production ex vivo." (PMID 36319895, 2023). "Meanwhile, we demonstrated that ZQFZ decreased the protein levels of CTLA4 and PD-L1 in colorectal tumors of ApcMin/+ mice." (PMID 35680568, 2022). "Using intravenous delivery of our oncolytic virus-driven T-cell-based combination immunotherapy to target colorectal tumors and CTLA4-positive Treg cells in the microenvironment of the cancer, it has been seen that lung metastases of colorectal tumors have significantly decreased." (PMID 38243252, 2024). "Using this process, colorectal tumor cells have been shown to acquire immune receptors (e.g., CD45 and CD4) and functional immunoregulatory molecules (e.g., Tim3, CTLA-4 and PD-1) from T cells, thus enhancing tumor immunosuppression." (PMID 35269922, 2022). "Previous studies have found that the use of PD-1, PD-L1, and CTLA4 inhibitors can have a better immune effect on refractory (MSI-H and MSS) colorectal tumors, but the recurrence and adverse reactions have been reported in the number of patients." (PMID 35401882, 2022). "We found that the expression levels of PD-1, CTLA-4, TIM-3, TIGIT, PD-L1, and galectin-9 were significantly higher in colorectal tumor tissues, compared with colon normal tissues." (PMID 30081950, 2018). "In this study, we found that expression of ICs including PD-1, CTLA-4, TIM-3, TIGIT, and IC ligands including PD-L1 and galectin-9 was significantly higher in colorectal tumor tissues compared with normal tissues." (PMID 30081950, 2018). "Interestingly, we found that ICs including PD-1, CTLA-4, TIM-3 and TIGIT, and IC ligands including PD-L1 and galactin-9 were significantly upregulated in colorectal tumor tissues (TT), compared with colon normal tissues (NT)." (PMID 30081950, 2018). "Synergistic antitumor activity in mouse MC38 and CT26 colorectal tumor models was observed with concurrent, but not sequential CTLA-4 and PD-1 blockade." (PMID 27610613, 2016). "We also observe a significant reduction in lung metastases of colorectal tumours through intravenous delivery of our oncolytic virus driven T-cell based combination immunotherapy to target colorectal tumours and FAP-positive stromal cells or CTLA4-positive Treg cells in the tumour microenvironment." (PMID 36405739, 2022). "Indeed, some dMMR-MSI-H colorectal tumors that initially displayed active cytotoxic CD8+ T cell (CTL) responses have been shown to raise immunosuppressive molecules such as PD-1, PD-L1 or CTLA-4 to counterbalance the cytotoxic environment, inducing tumor immune evasion." (PMID 35269922, 2022).
hypopituitarism (17 papers, 2019 to 2026). A condition of diminution or cessation of secretion of one or more hormones from the anterior pituitary gland. "Some agent-specific associations have been demonstrated in the literature, with hypopituitarism mostly seen following anti-CTLA-4 treatment and thyroid dysfunction being correlated with anti-PD-1 and anti-PD-L1 antibodies." (PMID 36672324, 2023). "A retrospective analysis of 11 Japanese patients that developed hypopituitarism during treatment with anti-PD-1 or anti-CTLA-4 suggested a positive association with HLA-DR15 (p = 0.0014)." (PMID 36672324, 2023). "Anti-CTLA-4 antibodies often cause hypopituitarism, while anti-PD-1/anti-PD-L1 antibodies cause thyroid dysfunction." (PMID 32610470, 2020). "Hypopituitarism is an endocrinopathy caused by ICIs, particularly anti-CTLA-4 mAb." (PMID 35468815, 2022). "Meanwhile, hypopituitarism and secondary adrenal insufficiency are more common in patients receiving anti-CTLA-4 therapy." (PMID 35468815, 2022). "The incidence rate of anti-CTLA-4 mAb-induced hypopituitarism is approximately 6%–8% as per previous reports." (PMID 35468815, 2022). "Several reports have revealed that the duration from treatment to ICI-induced hypopituitarism was shorter in patients treated with anti-CTLA-4 mAb therapy or combination therapy with ICIs than in those who received anti-PD-1 mAb therapy." (PMID 35468815, 2022). "Hypopituitarism as an irAE is more common in patients receiving anti-CTLA-4 antibodies than in those receiving anti-PD-1/anti-PD-L1 antibodies, with the reported incidences being approximately 10% and ≤1%." (PMID 32610470, 2020). "Although our study found only 71 cases of serous‐grade hypopituitarism among 12 336 patients (0.58%), 50 cases occurred with anti‐CTLA‐4 therapy among 5790 patients." (PMID 31679184, 2019). "Hypopituitarism onset has been reported at 8–16 weeks (95% CI) with anti-PD-1 antibodies, 0–48 weeks (95% CI) with anti-PD-L1 antibodies, and 4–10 weeks (95% CI) with anti-CTLA-4 antibodies." (PMID 41536580, 2026). "The most common biochemical abnormality in the CTLA-4 group was hypopituitarism." (PMID 41510421, 2025). "Moreover, the incidence rate of anti-PD-1/PD-L1-induced hypopituitarism is lower than that of anti-CTLA-4 mAb-induced hypopituitarism." (PMID 35468815, 2022). "Hypopituitarism often develops 4–10 weeks after treatment initiation due to anti-CTLA-4 antibodies." (PMID 32610470, 2020). "Likewise, among 45 cases of any‐grade hypopituitarism, 36 occurred with anti‐CTLA‐4 therapy among 1836 patients (1.96%)." (PMID 31679184, 2019). "In addition, while most cases of CTLA-4 inhibitor-induced hypopituitarism have imaging findings at the time of diagnosis, patients who received CTLA-4 inhibitors were not included in this study." (PMID 39553056, 2024).
pancreatic ductal adenocarcinoma (17 papers, 2018 to 2026). An infiltrating adenocarcinoma that arises from the epithelial cells of the pancreas. "This anti-CSF1 treatment sensitised resistant pancreatic ductal adenocarcinoma (PDAC) towards treatment with checkpoint inhibitors (anti-PD1 or anti-cytotoxic T-lymphocyte-associated protein 4 (anti-CTLA4))." (PMID 30577495, 2018). "Therefore, this study aimed to explore the relationship between CTLA-4 polymorphisms and sCTLA-4 and the risk of pancreatic ductal adenocarcinoma (PDAC) in an Egyptian population." (PMID 41141615, 2025). "Several clinical trials assessed the combination of immunotherapy targeting CTLA4 or PD-L1 with chemotherapeutic drugs as front-line treatment for pancreatic ductal adenocarcinoma." (PMID 41422078, 2025). "For instance, AK104 (PD-1+CTLA4) has been approved for platinum-refractory or metastatic cervical cancer, and KN046 (CD274+CTLA4) has entered Phase III clinical trials for pancreatic ductal adenocarcinoma (PDAC) and NSCLC." (PMID 38713378, 2024). "The combination of photon beam irradiation and anti-CTLA-4 antibody (C4) for the anti-tumor effect enhancement at local and distant tumors (abscopal tumors) was investigated using the pancreatic ductal adenocarcinoma (PDAC) mouse model." (PMID 35565217, 2022). "The combination of photon beam irradiation and anti-CTLA-4 antibody (C4) for the anti-tumor effect enhancement at local and distant tumors (abscopal tumors) was investigated using a pancreatic ductal adenocarcinoma (PDAC) mouse model." (PMID 35565217, 2022). "Additionally, research has indicated that CD40 agonists can enhance the effectiveness of immune checkpoint inhibitors, such as anti-PD1 and anti-CTLA4, in preclinical models of pancreatic ductal adenocarcinoma (PDAC)." (PMID 40003965, 2025). "Previous studies have shown that depletion of myofibroblasts in the tumor and reduction of fibrosis may significantly increase CTLA4 expression in ductal adenocarcinoma of the pancreas and improve the efficacy of anti-CTLA4 antibodies in mice." (PMID 35710350, 2022). "Presumably, combining anti-CSF1 treatment with checkpoint blockade such as via anti-PD1 and anti-CTLA4 antibodies may enhance immune cell anti-tumor activity and improved efficacy over single-agent treatment as was demonstrated in established pancreatic ductal adenocarcinoma tumors." (PMID 31552020, 2019). "Tregs found in the peritumoral LN of a pancreatic ductal carcinoma model expressed CTLA-4, and CTLA-4/CD80 ligation with DCs inhibited conventional CD4+ T cell tumor infiltration." (PMID 34177968, 2021). "Pancreatic ductal adenocarcinoma (PDAC) responds poorly to checkpoint blockade, such as anti-CTLA-4 and anti-PD-1." (PMID 32055023, 2020). "Similarly, in a murine model of pancreatic ductal carcinoma, the depletion of FAP+ stromal cells potentiated the antitumor effects of anti-CTLA4 and anti-PD-L1 therapy." (PMID 38558814, 2024).
uveitis (17 papers, 2014 to 2025). An inflammatory process affecting a part of or the entire uvea. "Ipilimumab (CTLA-4 inhibitor) was associated with the highest incidence rate ratio of uveitis (IRR = 30.5) among ICIs, exceeding even ipilimumab plus nivolumab combination therapy (IRR = 20.7)." (PMID 38337852, 2024). "In lung cancer patients, the risk of developing uveitis during their treatment course is more than seven times higher amongst those receiving combined PD-L1/CTLA-4 inhibitors therapy than either ICI monotherapy." (PMID 38337852, 2024). "Among recipients of the combinatory ICI regimens, cancer patients exposed to a combination of anti-PD-1 and anti-CTLA-4 exhibited elevated hazard ratios associated with uveitis development (HR: 5.04 [CI:3.55-7.16]) compared to their non-ICI comparators." (PMID 38264654, 2023). "It is suggested that, in patients treated with ICIs, inhibition of the PD-L1/PD-1 and CD86/CTLA4 pathways induces ocular inflammation, causing uveitis." (PMID 37604934, 2023). "Unfortunately, insufficient data precluded the analysis of uveitis risk among patients who received a combined regimen of anti-PD-L-1 and anti-CTLA-4." (PMID 38264654, 2023). "Uveitis associated with anti-CTLA-4 is described several times and ocular side effects affect about 1.3% of ipilimumab treated patients." (PMID 29195497, 2017). "The overall risk for uveitis significantly increases after 1 year, and a strong association is linked to nivolumab, a PD-1 inhibitor, which accounted for 32% of total uveitis cases but is most strongly associated with ipilimumab, a CTLA-4 inhibitor." (PMID 39595113, 2024). "Uveitis linked to CTLA-4 inhibitors is usually of mild grade, as is anterior uveitis." (PMID 39595113, 2024). "This selective targeting of the early stages of T-cell activation may theoretically make recipients of anti-CTLA-4 drugs more susceptible to developing autoimmune adverse events like uveitis." (PMID 38264654, 2023). "Lastly, regarding the mechanisms behind why CTLA-4 class of ICI is most associated with uveitis, it has been hypothesized that this class of drugs’ mechanism of action focused more on the proximal stages of T-cell activation." (PMID 38264654, 2023). "The CTLA-4 haplotype has been shown to be associated with other types of uveitis, and this can be due to differences in the pathogenesis mechanisms among different uveitis entities." (PMID 25097674, 2014). "Tables showing the indications, administration doses, and reported incidences of uveitis from CTLA-4 inhibitors phase I/II trials are found in Appendix A (Table A1)." (PMID 38337852, 2024). "We found that monotherapy with the anti-CTLA-4 class of ICI drugs had the highest hazard ratios for uveitis development compared to all other classes." (PMID 38264654, 2023). "Based on this study, we found that the prevalence of ophthalmoplegia in Asian, the combination therapy of PD-L1+CTLA4 inhibitors were significantly higher than uveitis or other ocular irAEs." (PMID 34504488, 2021). "Uveitis is more likely to occur in patients following ICI therapy with CTLA-4 inhibition than in those with PD1 inhibition." (PMID 34504488, 2021). "It has been suggested that the incidence of autoimmune events, which included colitis, pruritus, dermatitis, hepatitis, hypophysitis and uveitis, were positively correlated with the dose of anti-CTLA-4 antibody administered." (PMID 27071457, 2016). "Many other events were also reported with anti-CTLA-4 antibodies, including uveitis, organizing pneumonia, lupus nephritis, autoimmune cytopenia, and hemophilia A, as well as a recently published case of polymyalgia/giant cell arteritis." (PMID 26337719, 2015). "As part of a subgroup analysis on different combinatory treatment regimes, we also found that the combination of anti-PD-1 and anti-CTLA-4 exhibited elevated hazard ratios associated with uveitis development compared to their non-ICI comparators." (PMID 38264654, 2023).